RN7SL726P (RNA, 7SL, cytoplasmic 726, pseudogene)
Gene: Miscellaneous RNA gene on chromosome 9 (70,579,163 to 70,579,461, reverse strand). Ensembl gene ENSG00000272232.
Homologues: Orthologues: chimpanzee Metazoa_SRP (98% identical), macaque Metazoa_SRP (86% identical). Paralogues in human: RN7SL1 (83% identical), RN7SL2 (83% identical), RN7SL3 (81% identical), RN7SL186P (80% identical), RN7SL664P (80% identical), RN7SL296P (80% identical), RN7SL386P (80% identical), RN7SL479P (80% identical), RN7SL493P (80% identical), RN7SL575P (80% identical), RN7SL7P (80% identical), Metazoa_SRP (79% identical), and 704 more.